PGK1 (phosphoglycerate kinase 1)
Diseases named in the same sentence as PGK1 in open-access papers (continued):
Sharing a sentence is not in itself a finding about the gene and the disease.
glioblastoma (30 papers, 2017 to 2025). The most malignant astrocytic tumor (WHO grade IV). "PGK1-mediated phosphorylation of Beclin1 at Ser30 is positively associated with poor prognosis in glioblastoma." (PMID 36860848, 2023). "The inverse relationship between BNIP3 and PGK1 was unexpected, and together with the minimal associations seen between several other proteins, suggests a multi-level regulatory system of the hypoxic pathway in glioblastoma." (PMID 35419292, 2022). "In hepatocellular carcinoma and glioblastoma, PGK1 phosphorylation has been shown to facilitate glycolytic reprogramming, enhancing tumor cell adaptation to energy demands." (PMID 40529105, 2025). "Radio-gene therapy utilizes nanoparticles engineered for hypoxia-triggered RNA interference, silencing critical tumor-promoting genes such as PGK1, thereby significantly sensitizing tumors like glioblastoma to concurrent chemotherapy and radiotherapy." (PMID 40573996, 2025). "GQQ-792 is a non-ATP-competitive inhibitor and exhibits antitumour activity in vitro and in vivo by directly binding to PGK1 and inhibiting its kinase activity in U87-MG glioblastoma cells." (PMID 37723547, 2023). "The overexpression of PGK1 mRNA in glioblastoma patients correlates with poor prognosis and overall survival." (PMID 38139462, 2023). "PGK1 T243 phosphorylation induced by interleukin-6 (IL-6) secreted from polarized M2 macrophages induces tumor cell glycolysis and tumorigenesis in human glioblastoma multiforme." (PMID 37226192, 2023). "A previous study pointed out that phosphorylation modification is distinctly crucial for the PGK1 protein, accelerating the malignant development of glioblastoma by regulating the Warburg effect." (PMID 38098044, 2023). "This phosphorylation enhances PGK1-catalyzed glycolytic reactions by modulating their substrate affinities and has been correlated with human glioblastoma multiforme (GBM) malignancy and prognosis." (PMID 36588722, 2022). "PGK1 has been reported to interact with and phosphorylate Beclin1 under hypoxia to induce autophagy, promoting the proliferation of glioblastoma cells." (PMID 35058442, 2022). "IL-6 secreted by in situ macrophages regulated the direction of a PGK1-catalyzed reaction by increasing PDPK1-dependent PGK1 phosphorylation in glioblastoma cells, promoting glycolysis and proliferation of tumor cells." (PMID 35600367, 2022). "Study found that PGK1 acetylation affected brain tumorigenesis through mediating autophagy and the increased acetylation level of PGK1, which was correlated with the poor prognosis in glioblastoma." (PMID 34712204, 2021). "For example, in human glioblastoma multiforme, the activity of a key glycolytic enzyme phosphoglycerate kinase 1 (PGK1) is enhanced through phosphorylation at Threonine243." (PMID 32564010, 2020). "In human glioblastoma cells, the activity of the Pin1 isomerase drives the correct binding of Phosphoglycerate kinase 1 (PGK1) to the outer membrane translocase (TOM) complex allowing its mitochondrial translocation." (PMID 31614723, 2019). "P4HA1, an enzyme involved in collagen hydroxylation and hypoxia response, has been recently shown to regulate succinylation in glioblastoma by increasing intracellular succinate and enhancing PGK1 K191/K192 succinylation, which stabilizes PGK1 and promotes aerobic glycolysis via the HIF1α/ATF3 axis." (PMID 40463370, 2025). "The novel amphiphilic cationic block copolymer poly(MIs)-PEI was successfully synthesized for PTX and siPGK1 delivery with unique hypoxia-triggered properties, which presented efficient knockdown of PGK1 protein that offered enough energy for glioblastoma growth and metastasis." (PMID 37408007, 2023). "Also, it has been observed that glutamine starvation in glioblastoma cells promotes PGK1 acetylation leading to activation of the VPS34-Beclin1 complex to initiate autophagosomal formation." (PMID 38139462, 2023).
glioblastoma (continued). "In glioblastoma, ARD1 acetylates PGK1 at K388 to initiate autophagy, correlating with higher malignancy and poor prognosis." (PMID 41213956, 2025). "In glioblastoma, TME metabolic stress triggers ARD1-mediated PGK1 acetylation, promoting autophagosome formation and tumor survival." (PMID 41213956, 2025). "The agent inhibits hypoxic PGK1 and EGF/EGFR signaled protein kinase activity of PGK1 to phosphorylate Thr338 residue of PDHK1 in glioblastoma cells." (PMID 36077431, 2022). "It was shown in a recent report that PGK1, as a key kinase in glycolysis and the TCA cycle, regulates PDHK1 T338 phosphorylation and promotes tumorigenesis in glioblastoma." (PMID 30925862, 2019). "These authors showed that FAT1 is associated with HIF-1α expression, as well as with its targets PGK1 (Phosphoglycerate kinase 1) and VEGFA in human glioblastoma samples." (PMID 31010154, 2019). "ARD1 acetylates PGK1 at K388, which does not affect glycolysis, is specifically required for glutamine deprivation-induced PGK1-mediated autophagy in glioblastoma." (PMID 41184227, 2025). "In addition, PGK1 T243 phosphorylation correlates with PDPK1 activation, IL-6 expression, and macrophage infiltration in human glioblastoma (GBM) and correlates with the malignancy and prognosis of human GBM." (PMID 37491279, 2023). "Phosphoglycerate kinase 1 (PGK1) and Cofilin-1 (COF1) proteins were up-regulated in radioresistant astrocytomas and were previously identified as biomarkers for an unfavorable prognosis in glioblastoma." (PMID 31357616, 2019). "These include pyruvate phosphoglycerate kinase 1 (PGK-1) and hexokinase II (HKII), involved in the glycolytic pathway, and c-Met and VEGF, receptor tyrosine kinase drivers of the stem cell phenotype and neoangiogenesis in glioblastomas, respectively." (PMID 29097800, 2017). "In addition, PGK1 S203 and PDHK1 T338 phosphorylation levels were found to be positively correlated with each other, and both were correlated with PDH S293 inactivating phosphorylation levels and poor prognosis in patients with glioblastoma (GBM)." (PMID 31578148, 2019).
liver cancer (28 papers, 2017 to 2025). An epithelial or non-epithelial malignant neoplasm that arises from the liver. "The loss of PGK1 is associated with the inhibition of carcinogenesis and is also a marker of progression in gastric, oral, and liver cancer." (PMID 39684297, 2024). "The PGK1 acetylation was also found to promote its enzymatic activity and liver cancer cell metabolism, and significantly associate with poor prognosis of liver cancer patients." (PMID 34712204, 2021). "Overexpression of PGK1 has been shown to promote the proliferation and metastasis of liver cancer cells and is associated with poor prognosis, suggesting its potential carcinogenic role in liver cancer progression." (PMID 39315723, 2024). "PGK1 is also acetylated at K323, which promotes its enzymatic activity and cancer cell metabolism, resulting in the promotion of liver cancer cell proliferation and tumorigenesis." (PMID 41184227, 2025). "SIRT7 suppresses glycolysis by decreasing HIF-1 protein levels in MDA-MB-231 cells and deacetylating phosphoglycerate kinase 1 (PGK1) at the K323 site in liver cancer." (PMID 39372420, 2024). "For instance, acetylation of PGK1 at the K323 site is an important regulatory mechanism for promoting its enzymatic activity as well as liver cancer cell proliferation and tumorigenesis." (PMID 37723547, 2023). "P300/cyclic adenosine monophosphate responsive factor (PCAF) acetylated PGK1 K323 to promote its glycolytic enzymatic activity and liver cancer cell metabolism, while Sirtuin 7 deacetylated PGK1 K323 to repress its glycolytic enzymatic activity." (PMID 37226192, 2023). "Previous studies have confirmed that serum PGK1 levels in patients with liver cancer, pancreatic cancer and lung cancer are significantly higher than those in healthy controls." (PMID 35121728, 2022). "MiR-450b-3p is underexpressed in liver cancer and at least partly through inhibiting PGK1 to play a tumor suppressor effect." (PMID 33584825, 2021). "For instance, the lncRNA associated with microvascular invasion in hepatocellular carcinoma (MVIH) interacts with the antiangiogenic factor phosphoglycerate kinase 1 (PGK1) to reduce its secretion in hepatic cancer." (PMID 32992718, 2020). "P300 regulated the acetylation of PGK1 and promoted its enzymatic activity and cell metabolism in liver cancer cells." (PMID 33043000, 2020). "SIRT7 deacetylates phosphoglycerate kinase 1 (PGK1), resulting in reduced glycolysis and liver cancer cell proliferation." (PMID 32404984, 2020). "SIRT7 deacylates phosphoglycerate kinase 1 (PGK1), a key enzyme in glycolysis pathway, and suppresses PGK1 enzymatic activity in liver cancer cells." (PMID 30510540, 2018). "SIRT7 regulates acetylation at the K323 site of phosphoglycerate kinase 1 (PGK1), an important enzyme in glycolysis, decreases PGK1 enzyme activity and inhibits glycolysis in liver cancer cells." (PMID 30574122, 2018). "Interestingly, overexpression of PGK1 has been observed in different types of tumors including liver cancer, and downregulation of PGK1 has been proved to reduce cell proliferation and tumorigenesis." (PMID 36914921, 2023). "Also, the depletion of PGK1 dramatically reduced cancer cell proliferation and metastasis, indicating an oncogenic role of PGK1 in liver cancer progression." (PMID 28749413, 2017). "According to previous studies, acetylation at K323, located in its C-terminal domain of PGK1, enhanced its catalytic efficiency by increasing its affinity for ADP/ATP and promoted the proliferation, glycolysis, and tumorigenesis of liver cancer." (PMID 37741973, 2023). "Early studies have shown that PGK1 was activated by HIF-1 in colorectal cancer and liver cancer under hypoxia stress." (PMID 33941139, 2021). "Moreover, knockdown of BFSP1 significantly inhibited the expression of glycolysis-related proteins PKM2, GLUT1, PGK1, and LDHA in liver cancer cells, whereas overexpression of BFSP1 promoted the expression of the glycolysis-related proteins." (PMID 40097750, 2025).
liver cancer (continued). "Furthermore, the expression of MVIH in liver cancer patients is significantly negatively correlated with the angiogenesis inhibitor PGK1, suggesting that MVIH promotes liver cancer metastasis by inhibiting the secretion of PGK1." (PMID 31341758, 2019).
lung cancer (25 papers, 2006 to 2025). A malignant neoplasm involving the lung. "A LASSO regression model was constructed using the expression matrix of H1975 and H1975-BM51 cells, identifying AGO3, NCSTN, and PGK1 as hub genes associated with lung cancer BM." (PMID 40696604, 2025). "Furthermore, PGK1 was significantly upregulated in lung cancer tissues and associated with increased migratory and invasive capabilities of cancer cells." (PMID 41154605, 2025). "In recent years, the association between PGK1 and lung cancer has garnered increasing attention." (PMID 38163864, 2024). "The data suggested that the overexpression of PGK1 was strongly associated with a poor overall survival and a progression-free survival in lung cancer, especially in the adenocarcinoma subtype, which has been thought to be the most common type of lung cancer clinically." (PMID 34091600, 2021). "PFKP, PGAM1 and PGK1 are key metabolic enzymes in lung cancer, contributing to tumour progression and patient prognosis." (PMID 41154605, 2025). "Elevated PGK1 expression in IHC analysis was significantly correlated with poor outcomes in lung cancer patients." (PMID 41154605, 2025). "Another study has reported a strong correlation between the upregulation of PGK1 and the migratory potential of lung cancer cells." (PMID 38163864, 2024). "According to the validation, we observed a higher PGK1 expression in lung cancer samples compared to adjacent normal tissues." (PMID 34091600, 2021). "Taken together, these results indicated that we identified the characteristics of PGK1 as the key enzyme for promoting lung cancer migration, especially in the adenocarcinoma subtype." (PMID 34091600, 2021). "Consistently, the data from the microarray analysis (GSE7670) from GEO definitively demonstrated that PGK1 gene expression in the tumor portions was extensively higher than that in the paired normal adjacent tissues in lung cancer patients." (PMID 34091600, 2021). "Here, we found that phosphoglycerate kinase 1 (PGK1) up-regulation highly correlated with migratory/invasive activity of lung cancer cells and poorer outcomes in clinical lung cancer patients." (PMID 34091600, 2021). "We further validated PGK1 expression with two different probes (217356_s_at and 217383_at) in the lung cancer cohort from the Kaplan–Meier Plotter website." (PMID 34091600, 2021). "Significantly, the knockdown of PGK1 inhibited, while the forced expression of exogenous PGK1 promoted, the in vitro migratory activity of lung cancer cell lines that had highly or poorly expressed PGK1 protein, respectively." (PMID 34091600, 2021). "Taken together, these results lead us propose that PGK1 coordinates with HTATSF1 to promote lung cancer migration through protein–protein interactions." (PMID 34091600, 2021). "After IHC scoring, the high level of PGK1 combined with the high level of HTATSF1 staining significantly correlated with a poor overall survival and disease-free survival compared with a low level of PGK1 combined with a low level of HTATSF1 in lung cancer." (PMID 34091600, 2021). "We further examined the gene expression of PGK1 in lung cancer patients by analyzing the online TCGA database and the GEO meta-analysis cohorts." (PMID 34091600, 2021). "At present, studies have confirmed the correlation between PGK1 and immune/inflammation cells in breast and lung cancer." (PMID 34277429, 2021). "We inputted the TCGA dataset and multiple microarray-based clinical cohorts, and both found that PGK1 had the most significant potential in lung cancer." (PMID 34091600, 2021). "Next, we performed immunochemical analysis to detect the protein level of PGK1 in the lung cancer tissue array." (PMID 34091600, 2021). "Interaction between MetaLnc9 and PGK1 blocks ubiquitin-mediated degradation of PGK1, promoting lung cancer metastasis." (PMID 33004065, 2020).
lung cancer (continued). "The up-regulation of glycolytic enzymes, including PGK-1 in lung cancer and M2-type pyruvate kinase in colorectal cancer, has been reported and suggested to be useful for cancer screening." (PMID 17187689, 2006). "Moreover, we determined the expression of PGK1 with several typical genetic alteration events in lung cancer, including EGFR mutants, KRAS mutants, and ALK fusions in The Cancer Genome Atlas (TCGA) clinical cohort." (PMID 34091600, 2021). "In previous studies, we confirmed that PGK1 can control the migration ability of lung cancer cells." (PMID 34091600, 2021). "Among the different datasets, the lung cancer patients with PGK1 overexpression had a significantly reduced survival probability, suggesting that higher PGK1 expression likely contributed to the mechanisms of cancer progression, such as chemotherapy resistance and metastasis." (PMID 34091600, 2021). "Although PGK1 seemed to be a promising prognostic marker, its role in lung cancer is controversial." (PMID 22229091, 2011). "Besides, the protein expression of PGK1 was explored in lung cancer and pan-cancer contexts." (PMID 36358653, 2022). "Similar to PGAM, targeting phosphoglycerate kinase 1 (PGK1) to inhibit glycolysis has become a new therapeutic target in tumor tissues through regulating inflammation, and inhibition of PGK1 in macrophages can also reduce the production of inflammatory factors in lung cancer." (PMID 36119084, 2022). "Importantly, PGK1 could serve as an independent prognostic factor and positively correlated with recurrence and poor survival rates in the lung cancer patient cohorts." (PMID 34091600, 2021). "Importantly, PGK1 and its interaction partners have served as an independent prognostic factor and positively correlated with patient survival rate and recurrence status in lung cancer patients." (PMID 34091600, 2021). "Therefore, the role of PGK1 in lung cancer warrants further investigations." (PMID 22229091, 2011). "Transcriptome sequencing data from H1975 and H1975-BM51 cells were analyzed using LASSO regression to construct a lung cancer-BM model, identifying AGO3, NCSTN, and PGK1 as hub genes." (PMID 40696604, 2025). "LINC00963 promotes metastasis in non–small-cell lung cancer (NSCLC) by stimulating the AKT/mTOR pathway and by inhibiting the ubiquitination of phosphoglycerate kinase 1 (PGK1)." (PMID 37384249, 2023). "Six genes (PGK1, ENO2, GPI, PEKP, ALDOA, and ANGPTL4) were reported as hypoxia-related genes in lung cancer." (PMID 38248716, 2023). "For example, upregulation of LINC00963 can inhibit ubiquitination of PGK1 to activate the AKT/mTOR pathway, thus promoting the metastasis of lung cancer, and DLX6-AS1 promotes tumor proliferation by regulating the JAK/STAT pathway." (PMID 33981850, 2021). "PGK1 could mediate the activation of the AKT/mTOR pathway, thus facilitating lung cancer metastasis." (PMID 35242214, 2022). "This evidence supports the hypothesis that the PPI between PGK1 and HTATSF1 may promote lung cancer metastatic ability." (PMID 34091600, 2021). "Through a two-way model, we confirmed that PGK1 and HTATSF1 could directly bind in lung cancer cells." (PMID 34091600, 2021). "GBP1 has been shown to promote proliferation, migration, and metastasis in lung cancer by binding to indoleamine 2,3-dioxygenase 1 (IDO1) and to enhance resistance to epidermal growth factor receptor (EGFR) inhibitors by interacting with phosphoglycerate kinase 1 (PGK1)." (PMID 40975978, 2025). "However, our data showed that PGK1 expression did not correlate with genetic alterations in lung cancer." (PMID 34091600, 2021). "Similarly, the RNA level from in-silico analyses with next-generation sequencing assays showed PGK1, rather than PGK2, overexpression in several malignant lung cancer cells." (PMID 34091600, 2021).